HNF4A (hepatocyte nuclear factor 4 alpha)
Diseases named in the same sentence as HNF4A in open-access papers (continued):
Sharing a sentence is not in itself a finding about the gene and the disease.
MODY (continued). "Several genetic subtypes of MODY exist, with the most common being mutations in HNF1A, HNF4A, and GCK genes." (PMID 40777711, 2025). "In HNF4A-MODY, for instance, a father and son transitioned from suboptimal control to HbA1c values in the mid-6% and high-5% range with GLP-1 RAs), accompanied by fewer hypoglycaemic events." (PMID 41262822, 2025). "There is a paucity of research investigating the long-term follow-up and management strategies for patients diagnosed with HNF4A-MODY." (PMID 40589512, 2025). "A study from the UK Biobank provides robust statistical evidence supporting the fact that mutations in HNF1A, HNF4A, GCK, and KCNJ11 are among the most common well-established forms of MODY." (PMID 40149950, 2025). "In both HNF1A- and HNF4A-MODY, tirzepatide has since been used in routine practice to achieve better glucose and weight outcomes, while allowing patients to reduce or discontinue other agents." (PMID 41262822, 2025). "In contrast, genetic testing of 272 German and Austrian children with suspected MODY revealed GCK mutations in 62% of cases, HNF1A mutations in 31%, and HNF4A mutations in 4%." (PMID 41153735, 2025). "Among Japanese patients with MODY, mutations in GCK, HNF1A, HNF4A, and HNF1B genes were detected in 39.2%, of which the proportion of GCK gene mutations was 21.6%." (PMID 39902162, 2024). "At least 14 types of MODY have been reported, among which HNF4A-MODY (MODY1) accounts for 3.8% of cases in the Japanese pediatric MODY population." (PMID 38745825, 2024). "Genetic variants in HNF4A and HNF1A are known to be causal for MODY (through a beta cell defect) and have also been robustly associated with T2D risk, implicating a clear role in regulating pancreatic beta cell function." (PMID 38909044, 2024). "The majority of MODY cases result from mutations in the GCK genes encoding glucokinase (GCK MODY) and the hepatocyte nuclear factor genes HNF1A and HNF4A." (PMID 39420387, 2024). "Regarding treatment, the percentage of patients with HNF1B-MODY treated with insulin was significantly higher than that of patients with HNF4A-MODY when compared with patients with T1DM (median 65.7% versus 36.4%, P = 0.00001 each)." (PMID 37016461, 2023). "It has been suggested that HNF1A/HNF4A-MODY can present at up to 45 years of age and should be included as an age cut-off to consider all possible cases of this MODY subtype." (PMID 37234800, 2023). "The majority of patients with a genetic a diagnosis of MODY (>80%) will have mutations in the HNF1A, HNF4A or GCK genes, and a genetic diagnosis of these subtypes has important implications for precision medicine‐based clinical care." (PMID 35445424, 2022). "The reduced penetrance of HNF1A/HNF4A-MODY in clinically unselected cohorts was largely consistent with the setting in which they were identified." (PMID 36257325, 2022). "The most commonly found cases arise from mutations in GCK, HNF4A, HNF1A and HNF1B, accounting for up to 80% of all diagnosed MODY." (PMID 35008927, 2022). "People with MODY and heterozygous HNF1A or HNF4A mutations are also highly sensitive to sulfonylureas." (PMID 35618782, 2022). "Mutations in fourteen different genes have been so far reported to cause several MODY subtypes (OMIM # 606391), the most common of which are due to mutations in GCK, HNF1A, HNF4A and HNF1B." (PMID 35052457, 2022). "MODY is primarily caused by a defect in pancreatic β-cells’ glucose-stimulated insulin production, highlighting the critical functions of HNF1A and HNF4A in -cells." (PMID 36037214, 2022). "Some variants with substantial expression effects are associated with MODY, such as promoter mutations in GCK, HNF1A or HNF4A or neonatal diabetes with SNPs in the CC element of the INS promoter." (PMID 35008927, 2022). "One limitation of current MPC is that it is only validated for the three most common subtypes of MODY (HNF4A, GCK and HNF1A) when there are at least 1 genes known to cause autosomal‐dominant monogenic diabetes." (PMID 35822264, 2022).
MODY (continued). "Among these genes, heterozygous mutations in HNF1A, HNF4A, and GCK have been identified as the root cause of more than 90% of MODY cases." (PMID 34421822, 2021). "The hyperinsulinaemic hypoglycaemia can be detected in the early life of HNF4A-MODY carriers, leading to MODY manifestation later on." (PMID 34299172, 2021). "In this study, we focused on the four most common MODY genes (HNF4α, GCK, HNF1α, and HNF1β) and performed screening analysis of 45 Japanese pediatric patients who were between 2.8 and 17 years of age at diagnosis." (PMID 34746319, 2021). "Common causes of MODY are genetic defects of GCK (Glucokinase), HNF1A (hepatocyte nuclear factor 1-alpha) and HNF4A (hepatocyte nuclear factor 4-alpha), which are involved in glucose sensing and glycemic regulation." (PMID 34944640, 2021). "The most common subtypes of MODY are associated with mutations in the genes GCK, HNF1A, HNF4A, and HNF1B; among them, up to 70% of cases are caused by mutations in GCK and HNF1A." (PMID 33477506, 2021). "Seven out of 31 index patients (22.6%) were confirmed as MODY with variants in genes encoding GCK, HNF1A, HNF1B, HNF4A, and PDX1." (PMID 34373539, 2021). "The most common forms of MODY are caused by mutations in the glucokinase gene (GCK-MODY) and hepatocyte nuclear factor genes (HNF1A-, HNF1B- and HNF4A-MODY) which together are responsible for around 99% of all MODY cases." (PMID 34299172, 2021). "While HNF4α has been well studied in the development of MODY, its role in tumorigenesis is not fully understood." (PMID 34771521, 2021). "The frequency of mutations in the major MODY genes (HNF4A, GCK, and HNF1A) has been shown to be extremely low among Korean patients with MODY." (PMID 33663443, 2021). "In another MODY genetic screening study of 76 unrelated families, GCK, HNF1A and HNF4A accounted for 18.42%, 15.79% and 2.63% of all MODY cases, respectively." (PMID 34421822, 2021). "Pathogenic mutations in GCK, HNF1A, HNF1B, HNF4A, and PDX1 confirmed MODY in 7 families, giving an overall positivity rate of 22.6% in this cohort." (PMID 34373539, 2021). "GCK, HNF4A, and HNF1A were the most frequently reported pathogenic genes causing MODY in Europeans, which accounts for approximately 94% of cases." (PMID 32411229, 2020). "The GCK, HNF1A, and HNF4A genes were sequenced in 46 unrelated patients that had at least two of the three classical clinical criteria for MODY (age at diagnosis, family history, and clinical presentation)." (PMID 31968686, 2020). "Low carbohydrate diet or low-dose sulfonylureas are used to manage HNF4A-MODY initially but insulin therapy is usually required in advanced disease or during pregnancy." (PMID 33292863, 2020). "The beneficial role of glucagon-like peptide-1 receptor agonists (GLP-1 RAs) in the management of patients with HNF4A-MODY has recently been reported." (PMID 33292863, 2020). "Maturity-onset diabetes of the young (MODY), a monogenic form of diabetes, can result from mutations in one of the genes expressed in β-cell that include GCK, HNF1A, HNF1B, HNF4A, PDX1, and B2M." (PMID 33113859, 2020). "After genetic analysis, diabetics (n = 46) with HNF1A, HNF1B, HNF4A, GCK gene mutations (diagnosed as MODY) and diabetics (n = 30) with HNF1B, HNF4A, GCK gene SNPs were excluded." (PMID 31109344, 2019). "In 216 (87%) patients, a diagnosis related to one of the three genes commonly associated with MODY (GCK, HNF1A, and HNF4A) was made, GCK accounting for 44% of all cases." (PMID 31291970, 2019). "The majority of MODY cases are accounted for by mutations in one of four genes: the transcription factors, hepatocyte nuclear factor 1-alpha (HNF1A), 4-alpha (HNF4A), 1-beta (HNF1B) and the enzyme, glucokinase (GCK)." (PMID 30377832, 2018). "In this study, we found that higher HbA1c levels and BMI at genetic diagnosis were associated with reduced success on sulfonylurea treatment in participants with HNF1A/HNF4A-MODY." (PMID 30229274, 2018).
MODY (continued). "A total of 4.1% of individuals had likely pathogenic or pathogenic variants in the commonest MODY genes (HNF1A, HNF4A, HNF1B, GCK or INS)." (PMID 30377832, 2018). "Diagnosis of MODY is mainly relying on the sequential screening of the three marker genes like hepatocyte nuclear factor 1 alpha (HNF1α), hepatocyte nuclear factor 4 alpha (HNF4α), and glucokinase (GCK)." (PMID 29867778, 2018). "Individuals with HNF1A- or HNF4A-MODY are optimally treated with low-dose sulfonylureas because of an increased pancreatic insulin secretory response to sulfonylureas and increased insulin sensitivity to the insulin secreted." (PMID 30229274, 2018). "Compared to GCK, HNF1A, HNF4A, and HNF1B, protein truncating mutations in the other MODY genes are less frequent causes of MODY." (PMID 29207974, 2017). "Mutations in the GCK, HNF1A, HNF4A, and HNF1B genes are the most common causes of MODY in the UK, and they represent different clinical characteristics respectively." (PMID 28105082, 2017). "We therefore recommend regular ultrasonography monitoring from 28 weeks’ gestation if the father has HNF4A MODY." (PMID 28556992, 2017). "Mutations in hepatocyte nuclear factor 4 alpha, (HNF4A, MODY1), glucokinase (GCK, MODY2), hepatocyte nuclear factor 1 alpha (HNF1A, MODY3) result in most common forms of MODY." (PMID 26300908, 2015). "HNF4A-MODY caused by mutations in the HNF4A gene is relatively less common than HNF1A mutations and accounts for approximately 5% of MODY cases worldwide." (PMID 23803251, 2013). "HNF4α has been extensively studied in hepatocytes and pancreatic β-cells for its role in development of MODY (maturity onset diabetes of the young) and T2D." (PMID 23468175, 2013). "To provide a molecular validation of these clinical findings, we turned to a cellular model of MODY where suppression of HNF1A or HNF4A function in INS-1 cells is achieved through the expression of DN-HNF1A or DN-HNF4A mutants." (PMID 23803251, 2013). "The most common MODY forms are caused by mutations in the glucokinase gene (GCK) and the hepatocyte transcription factor genes HNF1A and HNF4A." (PMID 22662265, 2012). "MODY patients fail to properly secrete insulin in response to glucose challenge and β-cell-specific knockout of HNF4α in mice results in reduced GSIS." (PMID 22359515, 2012). "Functionally, the acquisition of cytosine methylation at this promoter may reduce HNF4A expression in IUGR offspring, consistent with the inherited loss-of-function mutations in HNF4A that lead to an autosomal dominant form of maturity onset diabetes of the young (MODY)." (PMID 20126273, 2010). "In one family a balanced translocation between chromosomes 3 and 20, involving the promoter of HNF4A, co-segregated with MODY." (PMID 19216786, 2009). "HNF4α's role in MODY originates from its function as a β cell transcription factor that influences glucose induced insulin secretion." (PMID 20003313, 2009). "GCK-MODY was most common, followed by HNF4A and the lower-penetrance RFX6-MODY." (PMID 41288518, 2026). "Notably, transitioning to GLP-1RA treatment in individuals with HNF4A-MODY continues to demonstrate positive outcomes, even after an extended disease duration." (PMID 40589512, 2025). "Most often, MODY is caused by LOF variants in the coding regions of TF genes, but it can also be due to LOF variants in the cis-regulatory elements (CREs) of these genes, as has been shown, for example, for HNF1A and HNF4A." (PMID 41356216, 2025). "It is reasonable to hypothesize that patients with HNF4A-MODY may respond positively to meglitinides and GLP-1RAs; however, there is currently no empirical evidence to support this hypothesis." (PMID 40589512, 2025). "In many MODY-associated TF genes, homozygous LOF variants are generally thought to be embryonically lethal or result in early mortality, e.g., in GATA4, GATA6, HNF1A, HNF1B, HNF4A, and ONECUT1." (PMID 41356216, 2025). "Sulfonylureas are recognized as the standard first-line therapy for HNF4A-MODY." (PMID 40589512, 2025).
MODY (continued). "Nearly 90% of MODY cases are caused by variants in glucokinase (GCK, MODY2), hepatocyte nuclear factor 1-alpha (HNF1A, MODY3), or hepatocyte nuclear factor 4-alpha (HNF4A, MODY1), although the distribution of subtypes varies across populations." (PMID 41153735, 2025). "Hepatocyte nuclear factor 4 alpha (HNF4A) plays a crucial role in hepatic lipid metabolism and pancreatic β-cell function, with mutations in this gene linked to maturity-onset diabetes of the young (MODY)." (PMID 40926269, 2025). "Limited studies have explored the long-term management of patients diagnosed with HNF4A-MODY." (PMID 40589512, 2025). "A clinical diagnosis of MODY was considered, likely HNF1A or HNF4A mutation." (PMID 40777711, 2025). "Furthermore, the shift to GLP-1RA treatment in individuals with HNF4A-MODY continues to exhibit beneficial outcomes, even after an extended period of disease progression." (PMID 40589512, 2025). "Cell free DNA has been used to determine foetal genotype in GCK mutations and ABCC8 and may be beneficial in the future in others forms of MODY including HNF4A." (PMID 38933924, 2024). "Additionally, the patient did not develop lipid abnormalities, a complication often seen in patients with HNF4A-MODY." (PMID 38745825, 2024). "Therefore, identifying patients suspected of having HNF4A-MODY to pursue etiology-based therapies will contribute to better glycemic control and cost-effectiveness." (PMID 37711893, 2023). "In the aggregate of the three commonest genes for MODY, approximately 1:2,100 (95%CI 1:2,700 to 1:1,640) and 1:1,500 (1:1,750 to 1:1,250) individuals harbor a pathogenic variant for HNF1A, HNF4A, or GCK in the Geisinger and UK Biobank population cohorts, respectively." (PMID 36257325, 2022). "Similarly, an UK study demonstrated that the mutation pick-up rate of MODY genes (HNF1A, HNF4A, HNF1B, or GCK) in South Asian participants was 12.6%, lower than White European group (25.2%)." (PMID 35921062, 2022). "Insulin secretion, as assessed by the 60 min insulin-to-glucose ratio during an OGTT, was lower in HNF4α-MODY patients than in other MODY probands, indicating the presence of a more severe glucose-stimulated insulin secretory defect, although the comparison was made against only one subject." (PMID 34746319, 2021). "Among them, mutations in HNF4A, HNF1A, and GCK are the most common causes of MODY." (PMID 33663443, 2021). "In the Gulf Cooperation Council (GCC) region, a study from Oman examined 20 patients with suspected MODY but found no variants in three MODY genes (HNF4A, GCK, and HNF1A) sequenced at Exeter20." (PMID 34373539, 2021). "In the other two studies with Brazilian cohorts, approximately 60% of patients with clinical suspicion of MDM did not have mutations in HNF1A, GCK or HNF4A genes, but we did not test other MODY genes." (PMID 31576961, 2020). "In fact, HNF4A acts upstream of HNF1A, mutation of which can cause a form of MODY (MODY1)." (PMID 30155490, 2018). "Patients with atypical, less-severe presentations of HNF4A-MODY may be largely undiagnosed or misdiagnosed, but identification is important due to implications for treatment, pregnancy, and screening of family members." (PMID 29998026, 2018). "Interestingly, in this study population, utilizing the NGS we have identified MODY variants in NEUROD1, PDX1 and BLK genes in comparison to the more commonly reported HNF4A, GCK and HNF1A gene variants." (PMID 28095440, 2017). "To analyze the frequencies of the carriers of such mutations in our cohort, we analyzed genes (HNF1A, HNF4A, HNF1B, INS, ABCC8, and KCNJ11) in which a significant number of missense mutations have previously been reported in MODY, neonatal diabetes mellitus, or early onset diabetes." (PMID 29207974, 2017). "In contrast, HNF1A- and HNF4A-MODY patients can be treated with low-dose sulfonylureas." (PMID 28314945, 2017). "The most commonly mutated genes in MODY are HNF1A and GCK, followed by HNF4A and HNF1B." (PMID 29207974, 2017).